SNX27 (sorting nexin 27)
Description:
Involved in the retrograde transport from endosome to plasma membrane, a trafficking pathway that promotes the recycling of internalized transmembrane proteins. Following internalization, endocytosed transmembrane proteins are delivered to early endosomes and recycled to the plasma membrane instead of being degraded in lysosomes. SNX27 specifically binds and directs sorting of a subset of transmembrane proteins containing a PDZ-binding motif at the C-terminus: following interaction with target transmembrane proteins, associates with the retromer complex, preventing entry into the lysosomal pathway, and promotes retromer-tubule based plasma membrane recycling. SNX27 also binds with the WASH complex. Interacts with membranes containing phosphatidylinositol-3-phosphate (PtdIns(3P)). May participate in establishment of natural killer cell polarity. Recruits CYTIP to early endosomes.
Synonyms: KIAA0488; My014; MGC20471; DADAND; MRT1
Tractability: Antibody: UniProt places it where antibodies can reach, with medium confidence. PROTAC: ubiquitination databases record sites on it; its protein half-life has been measured.
Gene: Protein-coding gene on chromosome 1 (151,612,006 to 151,699,091, forward strand). Ensembl gene ENSG00000143376.
Subcellular location: Early endosome membrane; Cytoplasm, cytosol
Subcellular location (Human Protein Atlas): Vesicles
Gene Ontology:
Molecular function: phosphatidylinositol-3-phosphate binding; protein binding; phosphatidylinositol binding
Biological process: endocytic recycling; endosomal transport; endosome to lysosome transport; intracellular protein transport; regulation of synapse maturation; establishment of natural killer cell polarity; regulation of postsynaptic membrane neurotransmitter receptor levels; signal transduction
Cellular component: early endosome; early endosome membrane; glutamatergic synapse; immunological synapse; retromer complex; WASH complex; endosome; cytosol; postsynapse; postsynaptic early endosome; postsynaptic recycling endosome; Schaffer collateral - CA1 synapse
Genetic constraint (gnomAD): Loss-of-function variants: 20 observed, 55.87 expected, observed/expected ratio (o/e) 0.36, 90% interval 0.25 to 0.52. The upper end of that interval is the gene's LOEUF score, 0.52, which puts it in group 2 of 6, group 1 being the genes least tolerant of losing a copy. Missense variants: 457 observed, 573.25 expected, observed/expected ratio (o/e) 0.8, 90% interval 0.74 to 0.86. Synonymous variants: 250 observed, 236.34 expected, observed/expected ratio (o/e) 1.06, 90% interval 0.95 to 1.17.
Homologues: Orthologues: dog SNX27 (99% identical), guinea pig SNX27 (99% identical), mouse Snx27 (99% identical), rabbit SNX27 (98% identical), chimpanzee SNX27 (97% identical), macaque SNX27 (97% identical), pig SNX27 (97% identical), rat Snx27 (96% identical), tropical clawed frog snx27 (87% identical), zebrafish snx27b (82% identical), zebrafish snx27a (78% identical), Drosophila melanogaster Snx27 (52% identical), and 1 more. Paralogues in human: SNX17 (19% identical), SNX31 (16% identical).
Diseases named in the same sentence as SNX27 in open-access papers:
SNX27 is named in the same sentence as 41 diseases in open-access papers, as found by Europe PMC text mining. Sharing a sentence is not in itself a finding about the gene and the disease. The quoted sentences say what the papers report.
Down syndrome (13 papers, 2014 to 2024). "SNX27 has also been associated with various human conditions, such as Alzheimer’s disease, epilepsy, and Down syndrome." (PMID 38903913, 2024). "SNX27/retromer downregulation is strongly linked to Down’s Syndrome (DS) via glutamate receptor dysfunction and to Alzheimer’s Disease (AD) through increased intracellular production of amyloid peptides from amyloid precursor protein (APP) breakdown." (PMID 33937239, 2021). "SNX27, an endosome-associated cargo adaptor, is involved in developmental and neurological diseases, such as Down syndrome, Alzheimer's disease, infantile myoclonic epilepsy, hydrocephalus, and neuropathic pain." (PMID 30619032, 2018). "SNX27-deficiency causes cognitive impairment and contributes to the pathologies of Down syndrome by regulating glutamate receptor recycling and contributes to Alzheimer disease pathologies by controlling APP processing." (PMID 30619032, 2018). "Down's syndrome causes overexpression of miR-155, a chromosome 21–encoded microRNA that negatively regulates C/EBPb, thereby reducing sorting nexin 27 (SNX27) expression and resulting in synaptic dysfunction." (PMID 26648852, 2015). "Indeed, the de-regulation of SNX27 expression associated with Down’s syndrome, is considered to lead to synaptic dysfunction, in part, through reduced SNX27-mediated AMPA receptor trafficking." (PMID 34251337, 2021). "A case in point is sorting nexin-27 (SNX27), in which destabilised expression is associated with Down’s Syndrome and coding mutations are observed in patients with pleomorphic phenotypes that have at their core epilepsy, developmental delay and subcortical white matter abnormalities." (PMID 34251337, 2021). "Deficiencies in SNX27 function are associated with Down syndrome and epilepsy." (PMID 33374212, 2020). "Deficiencies in SNX27 function have been associated with Down syndrome and epilepsy." (PMID 31775031, 2019). "Increasing SNX27 levels in the hippocampus of Down syndrome mice improves synaptic and cognitive impairments." (PMID 38903913, 2024). "Such a pleiotropic role is entirely consistent with the complex phenotype observed in SNX27 null mice and provides insight into functional effects of reduced SNX27 expression that has been observed in AD, Down’s syndrome and infantile myoclonic epilepsy." (PMID 28399507, 2017). "Restoration of SNX27 in the hippocampus of Ts65Dn Down syndrome mouse models rescues synaptic and cognitive deficits." (PMID 25152012, 2014). "SNX27 null mice are small and die early after birth, whereas heterozygous mice show Down Syndrome (DS)-like cognitive impairment, which was recovered after SNX27 reconstitution in these mice, suggesting that one single gene can restore synaptic transmission and cognitive functions." (PMID 38166948, 2024). "T cells with partial SNX27 deficiency show a marked deficit in the CD4+ T cell pool, a hallmark of aging in mice and humans, and a well-characterized comorbidity of individuals with Down syndrome (DS)." (PMID 38166948, 2024). "For example, SNX27 expression is downregulated in human Down’s syndrome brains." (PMID 33374212, 2020). "In Down syndrome, miR-155 is upregulated, leading to synaptic dysfunction through downregulation of sorting nexin 27 (SNX27), although miR-155 can also suppress NMII activation, highlighting that miRNAs often regulate multiple targets that could function in disease pathology." (PMID 26542704, 2015). "Down syndrome brains show decreased SNX27 expression and reduced levels of CCAAT/enhancer binding protein β (C/EBPβ), a putative transcription factor for SNX27." (PMID 38903913, 2024). "Interestingly, reduced expression of SNX27 and its upstream regulatory transcription factor CCAAT/enhancer binding protein β (C/EBPβ) has been observed in Down syndrome brains." (PMID 25152012, 2014).
breast carcinoma (7 papers, 2016 to 2023). "We have previously demonstrated that loss of SNX27 dramatically reduces tumor growth and proliferation in breast cancer cells, which was further confirmed via mouse xenograft models." (PMID 36612066, 2022). "Another study investigating the associations of SNX27 and breast cancer metastasis revealed that SNX27 directly interacts with MT1-MMP, a key enzyme recruited by invadopodia for degradation and remodeling of the extracellular matrix." (PMID 36612066, 2022). "Understanding the underlying cell biology remains important for uncovering specific mechanisms underlying the role of SNX27 in breast cancer." (PMID 33937239, 2021). "SNX27 was recently found to be associated with EMT in breast cancer cells." (PMID 29868263, 2018). "In certain breast cancer cells, SNX27 is associated with the proper trafficking of MT1-MMP to the cell surface and the defect in SNX27 function leads to the impairment of MT1-MMP-mediated ECM destruction." (PMID 37681919, 2023). "SNX27 increases expression of vimentin and claudin−5 proteins, both of which promote tumor growth, and SNX27 has been proposed as a potential breast cancer biomarker." (PMID 33937239, 2021). "In breast cancer cells, SNX27 knockdown results in reduced motility, lower proliferation, less colony formation, and upregulated E−cadherin and β−catenin expression levels." (PMID 33937239, 2021). "The Cancer Genome Atlas database reveals SNX27 is highly expressed in invasive breast cancer tissue." (PMID 33937239, 2021). "The role of SNX27 should be further studied in a chemical-induced or a transgenic breast cancer model." (PMID 31182056, 2019). "In the current study, we also detected that knockdown of SNX27 significantly suppressed the expression of Vimentin in breast cancer cells." (PMID 31182056, 2019). "In order to compare the difference in expression of SNX27 in different malignant breast cancer cell lines, we collected 7 breast cancer cell lines with different levels of aggression." (PMID 31182056, 2019). "The importance of SNX27 in breast cancer development was confirmed in vivo with the xenograft nude mouse model." (PMID 31182056, 2019). "We wound expect a greater effect on cellular proliferation and the EMT pathway after complete knockout of the SNX27 from the breast cancer cells." (PMID 31182056, 2019). "Collectively, knockdown of SNX27 markedly suppressed the proliferation, migration and colony formation ability of breast cancer cells." (PMID 31182056, 2019). "SNX27 negatively influences Wnt signalling, we wondered that SNX27 plays a role in the migration of breast cancer cells." (PMID 26744382, 2016). "Consistently, over-expression of SNX27 inhibits migration of breast cancer cells, whereas SNX27 knockdown enhances the cell migration." (PMID 26744382, 2016). "SNX27 promotes breast cancer metastasis, and the elevated expression of SNX27 could be related to the marginally shorter survival of the patients." (PMID 35024436, 2022). "Overall, knockdown of SNX27 reduced the growth of MDA-MB-231 breast cancer cells." (PMID 31182056, 2019). "However, whether SNX27 affects breast cancer has not been explored." (PMID 31182056, 2019).
Hydrocephalus (6 papers, 2017 to 2023). Hydrocephalus is an active distension of the ventricular system of the brain resulting from inadequate passage of CSF from its point of production within the cerebral ventricles to its point of absorption into the systemic circulation. "A very recent publication, that does not study AQP4, describes that young postnatal Vps35 conditional KO mice develop neonatal hydrocephalus, similar to that of Snx27−/− mice, with deficient ependymal cells differentiation and ciliogenesis." (PMID 34002021, 2021). "Knockout of SNX27 reduced the number of ependymal cells and cilia density, leading to severe postnatal hydrocephalus." (PMID 37008045, 2023). "Constitutive Snx27−/− mice develop severe hydrocephalus soon after birth, showing ependymal deciliation and differentiation defects with complete penetrance." (PMID 34002021, 2021). "Here we identify Kidins220 as a key determinant in the control of brain water homeostasis, ventricular enlargement and hydrocephalus pathology by molecular mechanisms that involve the unexpected expression regulation of SNX27-retromer components, which in turn controls AQP4 turnover." (PMID 34002021, 2021). "Furthermore, the contributions of SNX27 in a wide range of neurological diseases have been characterized ranging from infantile myoclonic epilepsy and hydrocephalus, to drug addiction, and neuropathic pain." (PMID 30619032, 2018). "The recycling of endocytosed transmembrane proteins (cargos) from early endosomes back to the plasma membrane might be involved in ventriculomegaly development, as suggested by the presence of severe postnatal hydrocephalus in mice lacking sorting nexin 27 (Snx27)." (PMID 34002021, 2021).
viral infection (6 papers, 2021 to 2025). "In this study, we explained the underlying mechanisms of fish encoding the Snx27 gene in immune regulation and viral infection." (PMID 39494909, 2024). "Among the genes chosen for examination, only the retromer-associated adaptor SNX27 was required, highlighting the importance of the retromer complex over the retriever one for virus infection." (PMID 33574281, 2021). "Overexpression of JAK1, TYK2, MAP2K1, IFNG, TRPM2, and ADCY9 significantly inhibited viral infection, whereas overexpression of SNX27, GATA4, EHMT2, PCBP2, SMARCA4, and SLX4 enhanced viral infection." (PMID 40530850, 2025). "Because ACE2 uses its C-terminal PBM to engage with SNX27, we asked whether ACE2Δ3 disrupting the interaction with SNX27 exhibits the same behavior as the depletion of SNX27 during viral infection." (PMID 35022217, 2022). "It has been demonstrated that the interaction of Snx27 and the L2 minor capsid protein of human papillomavirus (HPV) is involved with viral genome trafficking and promoting viral infection and replication." (PMID 39494909, 2024). "Since we have established the link between ACE2 and SNX27, it is intriguing to know how the interaction between ACE2 and SNX27 affects viral infection." (PMID 35022217, 2022).
Cognitive impairment (5 papers, 2015 to 2024). Abnormal cognition is characterized by deficits in thinking, reasoning, or remembering. "SNX27 downregulation in neurons, as the result of Trisomy 21 (T21), has been linked with cognitive deficits due to impairment of AMPA and NMDA receptor recycling." (PMID 38166948, 2024). "SNX27 is enriched in brain, and has been implicated as a major contributor to intellectual impairment in DS." (PMID 29632483, 2018). "Moreover, SNX27 deficiency is an important contributor for synaptic and cognitive impairment in DS." (PMID 29632483, 2018). "At the neuronal synapse, SNX27 recycles PDZ-binding receptors and its defective expression is associated with synaptic dysfunction and cognitive impairment." (PMID 35095913, 2021). "In our previous work, we found that SNX27 haploinsufficiency disrupts glutamate receptor recycling, leading to synaptic and cognitive deficits." (PMID 33330482, 2020). "Taken together, dysregulation of a microRNA-155-C/EBPβ-SNX27 pathway contributes to synaptic and cognitive impairment in DS brains." (PMID 29632483, 2018). "Moreover, we found that Snx27+/– mice featured synaptic dysfunction and cognitive impairment, as well as the reduction in postsynaptic AMPA and NMDA receptors compared with that in Snx27+/+ mice." (PMID 33330482, 2020).
Alzheimer disease (4 papers, 2018 to 2024). A progressive, neurodegenerative disease characterized by loss of function and death of nerve cells in several areas of the brain leading to loss of cognitive function such as memory and language. "In addition, SNX27 partial loss enhances amyloid precursor protein processing, linking defects in SNX27 expression to Alzheimer ́s disease." (PMID 38166948, 2024). "Therefore, dysregulated SNX27 functioning has been reported in several neurological and degenerative diseases, such as Alzheimer’s disease." (PMID 36612066, 2022).
epilepsy (4 papers, 2019 to 2021). A brain disorder characterized by episodes of abnormally increased neuronal discharge resulting in transient episodes of sensory or motor neurological dysfunction, or psychic dysfunction. "To provide a broader view of SNX27-associated pathologies, we performed proteomics in rat primary neurons to identify SNX27-dependent cargoes, and identified proteins linked to excitotoxicity, epilepsy, intellectual disabilities, and working memory deficits." (PMID 34251337, 2021). "Furthermore, SNX27 associates with epilepsy and patients with SNX27 variants display seizures, developmental delay, behavioral disturbance, and subcortical brain abnormalities." (PMID 33931804, 2021). "Indeed, SNX27 dysfunction has been extensively shown to underlie excitatory synaptic defects associated with DS and epilepsy." (PMID 33931804, 2021). "Still, SNX27 pivotal role in NLGs trafficking unveils a putative role for SNX27 in pathologies that display aberrant inhibitory synaptic transmission, like mood disorders, epilepsy, and autism, among others." (PMID 33931804, 2021). "Authors observed that distinct variants of SNX27, possibly non-functional, occur in patients that display seizures, developmental delays, subcortical brain abnormalities, epilepsy, dysmorphic features, and impaired behavioral responses, among others." (PMID 33931804, 2021). "Given that hyperactivation of glutamate receptors may lead to excessive firing of neurons, we examined whether SNX27 overexpression results in epilepsy-like EEG." (PMID 33330482, 2020). "Patients lacking SNX27 expression or expressing predicted damaging inherited SNX27 variants display a range of neuronal phenotypes that include developmental delays, abnormal neurocognitive function, epilepsy, various types of seizure, and subcortical white matter abnormalities." (PMID 34251337, 2021).
developmental delays (3 papers, 2021). "SNX27 is important for higher-order processes, such as learning and memory, and patients with SNX27 variants display seizures, developmental delay, behavioral disturbance and subcortical brain abnormalities." (PMID 34835087, 2021).
COVID-19 (2 papers, 2022). A disease caused by infection with severe acute respiratory syndrome coronavirus 2. "Another possible common factor interconnecting the COVID-19 cycle of infection and PD is sorting nexin (SNX27), a protein involved in the endosomal recycling of many important transmembrane receptors." (PMID 35625737, 2022). "Therefore, SNX27, together with the entry pathway, may affect the tropism of SARS-CoV-2 and the outcome of COVID-19." (PMID 35022217, 2022).
intellectual disabilities (2 papers, 2020 to 2021). "Our results suggest SNX27 as a potential therapeutic target for treating intellectual disability and other neurodegenerative diseases." (PMID 33330482, 2020).
leukemia (2 papers, 2021 to 2022). A malignant (clonal) hematologic disorder, involving hematopoietic stem cells and characterized by the presence of primitive or atypical myeloid or lymphoid cells in the bone marrow and the blood. "Therefore, this study describes a novel role of SNX27 in the pathogenesis of leukemia causing virus as maintenance of GLUT1 cell surface levels via Tax-1/SNX27 interaction provides novel insight into post-infection regulation of HTLV-1 receptor molecules." (PMID 36612066, 2022). "An RNA interference (RNAi) screen in primary leukemia cells linked SNX27 loss to impaired cellular growth and viability; this suggests SNX27 could be considered as a diagnostic target." (PMID 33937239, 2021). "SNX27, the most unique member of the SNX family, has also been identified to play a role in leukemia." (PMID 36612066, 2022).
acute myeloid leukemia (1 paper, 2021). Acute myeloid leukemia (AML) is a group of neoplasms arising from precursor cells committed to the myeloid cell-line differentiation. "Sorting nexin 27 is also implicated in progression of acute myeloid leukemia (AML) with potential for therapeutic treatment strategies." (PMID 33937239, 2021).
Anxiety (1 paper, 2020). Intense feelings of nervousness, tension, or panic often arise in response to interpersonal stresses. "Taken together, these results indicate that SNX27 overexpression increases social interaction and reduces anxiety-like behavior in hSNX27 Tg mice." (PMID 33330482, 2020). "In the future study, the mechanisms by which SNX27 influences anxiety-like behavior need further investigation." (PMID 33330482, 2020). "The human-SNX27 transgenic (hSNX27 Tg) mice exhibited enhanced learning and memory, reduced anxiety-like behaviors, and increased social interaction, without seizure-like behavior." (PMID 33330482, 2020).